INS (insulin)
Diseases named in the same sentence as INS in open-access papers (continued):
Sharing a sentence is not in itself a finding about the gene and the disease.
Insulin resistance (continued). "The potential mechanism by which exercise attenuates HFD-induced insulin resistance involves increasing insulin sensitivity and glucose transport into contracting skeletal muscles." (PMID 24349059, 2013). "Defects in molecules of the insulin signaling pathway are now thought to be a major mechanism involved in the development of insulin resistance." (PMID 23762123, 2013). "T2D is a progressive metabolic disorder characterized by reduced insulin sensitivity, insulin resistance and pancreatic β-cell dysfunction." (PMID 23878802, 2013). "As expected, insulin resistance coefficient developed in DMN mice while nesfatin-1 treatment enhanced insulin sensitivity in DML and DMH significantly compared with DMN group." (PMID 24391760, 2013). "Insulin resistance can be conceptually defined as a resistance (impaired sensitivity) to insulin action at the tissue level." (PMID 24348462, 2013). "The metabolic phenotype of the MC4R KO rat was consistent with obesity-related insulin resistance, including elevations in plasma levels of cholesterol, triglycerides, free fatty acids, HbA1c, and insulin." (PMID 24400148, 2013). "In cancer patients with insulin resistance, the consequent high levels of circulating insulin, together with overexpression of the insulin receptor by the tumour cells, stimulate significant nonmetabolic effects." (PMID 23983688, 2013). "Inflammatory cytokines are known to contribute crucially to the development of insulin resistance by activating different kinases that disrupt insulin signaling." (PMID 23843683, 2013). "Insulin resistance was measured by assessment of the insulin requirement to maintain euglycaemia and repeated measurements of an insulin glycaemic index." (PMID 23840093, 2013). "Insulin resistance is defined as the decreased tissue response to insulin-mediated cellular actions and is the inverse of insulin sensitivity." (PMID 23356701, 2013). "In a rat model of type 2 diabetes, insulin was found to be increased due to the well-known phenomenon of insulin resistance." (PMID 23535335, 2013). "Von Hurst (2009) showed that vitamin D supplementation significantly improved insulin sensitivity and insulin resistance." (PMID 23443033, 2013). "Hepatic insulin resistance has been classically defined as an inability of insulin to suppress the hepatic glucose output." (PMID 24284392, 2013). "This suggests that while OGIS and LAR are both indices of whole body insulin sensitivity, adipocyte insulin resistance is reflected to a greater extent with LAR than with OGIS or HOMA." (PMID 23737780, 2013). "High-fat-diet/low lose of streptozotocin used for the induction of T2DM animal model characterized by abnormal metabolism of carbohydrates, fats and proteins, which is attributable to decreased insulin sensitivity leading to insulin resistance." (PMID 24131482, 2013). "In contrast, obese adolescents who were of lower birth weight had a greater incidence of insulin resistance and higher fasting insulin levels." (PMID 24555145, 2013). "To assess the long-term drug effect on insulin resistance, we performed insulin and glucose tolerance tests on the animals." (PMID 26251758, 2013). "A recent study has shown that IL-6 can inhibit insulin signaling in hepatocytes, and insulin resistance is a potential link between obesity and cancer development." (PMID 23819063, 2013). "It appears that hepatic insulin resistance was determined by the serum insulin concentration, corroborating the observation that insulin sensitivity and insulin secretion are reciprocal and inversely related." (PMID 23305533, 2013). "For comparison of glucose effect on TG levels in two groups, fasting insulin levels was measured and estimation of insulin resistance was calculated by HOMA index in order to assay the association among TG and insulin resistance and macrosomia." (PMID 24639763, 2013).
Insulin resistance (continued). "In cultured murine adipocytes, IL-6 production is strongly increased by TNF-α and induces insulin resistance by inhibiting glucose uptake and impairing insulin signaling and action." (PMID 24455420, 2013). "For example, some studies support that pancreatic β-cell dysfunction (i.e. impaired insulin production) contributes more to pathogenesis than insulin resistance." (PMID 24499129, 2013). "HD consumption improved (p < 0.05) plasma insulin (-9%) and insulin resistance (-11%, p = 0.03) as estimated by HOMA-IR compared with the LD group." (PMID 23638799, 2013). "Pancreatic β-cells must compensate for the pregnancy-induced insulin resistance with increased insulin secretion." (PMID 23467680, 2013). "The predictive ability of insulin resistance or insulin sensitivity for MetS in Japanese male subjects was checked by a one-year follow-up study." (PMID 24719625, 2013). "Vitamin E alone proved to be beneficial in decreasing the levels of free radicals and oxidative stress, it improve the action of insulin in patients with insulin resistance." (PMID 23618488, 2013). "G6Pase, which is abnormally active in insufficient insulin or insulin resistance, catalyzes the last enzymatic reaction that is common to gluconeogenesis and makes the liver releases glucose into the blood, resulting in the rising of blood glucose level." (PMID 23762123, 2013). "In order to evaluate insulin secretion and insulin resistance the homeostatic method was used (HOMA-B and HOMA-IR, respectively)." (PMID 23819910, 2013). "Insulin resistance has been broadly defined as “a state (of a cell, tissue, or organism) in which a greater than normal amount of insulin is required to elicit a quantitatively normal response”." (PMID 23424687, 2013). "Although some studies have indicated that smoking is related to reduced insulin sensitivity and the development of insulin resistance and type 2 diabetes, in our population there was no consistent association between smoking and fasting blood glucose." (PMID 24228807, 2013). "Treatment HFD-fed hamster with zerumbone (300 mg kg−1 per day) produced a similar effect to lipanthyl on insulin resistance, evidenced by reduction of fasting serum insulin levels and improved HOME-IR." (PMID 24223615, 2013). "A study in rodents showed that the infusion of resistin rapidly induced severe hepatic insulin resistance, resulting in a reduced insulin-mediated suppression of gluconeogenesis and increased glycogenolysis." (PMID 23762871, 2013). "A recent study has confirmed that anti-TNF-α therapy improves insulin resistance, beta-cell function, and reverted defects in the insulin signaling cascade in active RA patients with high insulin resistance." (PMID 23431244, 2013). "Adipo-IR, representing the circulating FFA influx relative to insulin, can be regarded as a good indicator of insulin resistance in studies of TG metabolism and NAFLD." (PMID 23688034, 2013). "Dysregulated hepatic fatty acid export, oxidation and desaturation and altered systemic and hepatic insulin sensitivity (insulin resistance) are among the main pathways in NAFLD pathogenesis." (PMID 24205128, 2013). "This provides a platform for the implementation and use of TNFα in insulin-resistance studies, as a factor to induce insulin resistance in the cells of interest." (PMID 24324517, 2013). "Glucosamine-induced ER stress causes insulin resistance in both human and rat skeletal muscle and impairs GLUT4 production and insulin-induced glucose uptake via an ATF6α-dependent decrease of the GLUT4 regulators MEF2A and PGC1α." (PMID 23716639, 2013). "The chemical composition and bioactivity of the teas is known to change with the level of fermentation, IFG and IGT are also two different states in insulin resistance and insulin secretion." (PMID 24260170, 2013). "Type 2 diabetes is characterized by insulin resistance (which affects skeletal muscle, liver and other insulin-sensitive tissues) and by defective insulin secretion." (PMID 23815800, 2013).
Insulin resistance (continued). "Insulin resistance in sepsis is due to a decreased effect of insulin, but also reflects an imbalance between insulin and its counter-regulatory hormones (cortisol, glucagon, growth hormone, and catecholamines)." (PMID 23999826, 2013). "In obesity and type 2 diabetes, insulin resistance is manifested by decreased insulin-stimulated glucose transport and metabolism in adipocytes and one mechanism is impaired insulin signaling." (PMID 23409006, 2013). "On the other hand, these results my support our current suggestion that there is a major need for a treatment aimed at improving tissue insulin sensitivity at low insulin resistance index-HOMA-IR values." (PMID 23819910, 2013). "In contrast, plasma insulin was elevated approximately 45 fold by obesity demonstrating severe insulin resistance expected from this model." (PMID 23527196, 2013). "One important link between AD and T2DM is insulin resistance in the CNS due to alterations in insulin receptor sensitivity and insulin signaling transduction." (PMID 23829668, 2013). "Typically, obesity promotes insulin resistance with a compensatory increase in insulin production via increased β-cell mass." (PMID 23437106, 2013). "It is well established that physical activity is beneficial for improving insulin sensitivity as individuals who maintain a physically active lifestyle are less likely to develop insulin resistance, impaired glucose tolerance, and type 2 diabetes." (PMID 24303139, 2013). "Several components of the insulin/PI3K pathway have been demonstrated to be involved in the development of insulin resistance upon chronic exposure to GH in several models." (PMID 23840818, 2013). "Insulin resistance at four weeks was assessed by insulin resistance indices, lnHOMA-IR and lnMatsuda, and AUC insulin during a 2-hour glucose tolerance test." (PMID 23577182, 2013). "Insulin resistance (IR) is a common pathophysiological state in which higher than normal concentrations of insulin are required to exert its biological effects in target tissues such as skeletal muscle, adipose tissue and liver." (PMID 23468892, 2013). "Median insulin resistance was higher in school age than in preschool cases, hence supporting the concept that the decrease of insulin sensitivity begins before pubertal transition." (PMID 23935878, 2013). "Increased vascular permeability due to structural alterations can then reduce insulin delivery to insulin-sensitive peripheral tissues, which in turn produces insulin resistance." (PMID 24499567, 2013). "With the exception of the defects of pancreatic β-cell mass, the decrease of insulin sensitivity in peripheral tissues and hepatic glucose overproduction are also mechanisms of development of hyperglycemia and insulin resistance." (PMID 23671868, 2013). "The natural history of T2D describes the process of the development from normal glucose tolerance (NGT) via so-called pre-diabetic states, which are characterized by higher insulin resistance and/or reduced insulin secretion, to T2D." (PMID 24502249, 2013). "Insulin resistance is a state in which normal concentrations of insulin produce a subnormal biologic response." (PMID 24228769, 2013). "As tyrosine levels increase, it is possible that, as in worms, the increases modify responses to insulin signaling and augment pre-existing insulin resistance in a harmful way." (PMID 24385923, 2013). "Recently, iron was implicated in the direct negative regulation of adiponectin production by adipocytes which resulted in insulin resistance in mice suggesting that the relationship between iron, adiponectin, and insulin sensitivity are tightly intertwined." (PMID 24065958, 2013). "Some possible mechanisms have been proposed based on elevated blood glucose, insulin resistance, elevated levels of insulin and insulin-like growth factor-I, higher prevalences of neurogenic bladder and sympathetic nerve dysfunction in the diabetic patients." (PMID 23286275, 2013).
Insulin resistance (continued). "A study in India with 2640 adolescents of both genders produced similar results; in eutrophic and overweight/obese adolescents, abnormalities in triglycerides, HDLc, basal insulin, and insulin resistance levels evaluated by HOMA-IR were higher in females." (PMID 23363783, 2013). "Glucosamine treatments have, however, previously been shown to induce cellular insulin resistance and block insulin responsive glucose transport." (PMID 23665900, 2013). "HepG2 cells were firstly exposed to high glucose to induce insulin resistance, and this was shown by reduced insulin-stimulated glycogen synthesis and elevated lipogenesis." (PMID 24066304, 2013). "Why are CIDE knockout mice protected from obesity and insulin resistance whereas in humans, expression levels inversely correlate with insulin sensitivity?" (PMID 23740690, 2013). "As insulin resistance normally develops during pregnancy, increased flux of dietary maternal glucose to the fetal circulation stimulates fetal insulin release." (PMID 24151621, 2013). "In NZO mouse, the hyperglycemia occupies a leading position despite the fact that the level of insulin is lower than that in other obese models because of the distinct peripheral insulin resistance and increased gluconeogenesis." (PMID 23671868, 2013). "Since obesity is one of the key risk factors for insulin resistance as well as T2D, the effects of SR4 on glucose and insulin sensitivity were tested." (PMID 24376752, 2013). "In individuals with insulin resistance this action of insulin is diminished, while other effects of insulin mediated via MAP-K pathway including stimulation of migration and growth of smooth muscle cells and production of PAI-1 are intact." (PMID 24164965, 2013). "Since PCOS is associated with defects in the activation and pancreatic dysfunction of β-cell insulin, it is important to understand the molecular mechanisms of insulin resistance in PCOS." (PMID 23844380, 2013). "Numerous multifactorial mechanisms that include genetic and environmental factors related to obesity are involved in the development of insulin resistance and impaired insulin secretion." (PMID 23308243, 2013). "Many observational and clinical studies have shown strong associations between serum and dietary magnesium and fasting insulin or insulin resistance, and impaired glucose metabolism or type 2 diabetes." (PMID 24322525, 2013). "Subsequently, IL-1β causes apoptosis of insulin producing β-cells, which results in reduced insulin secretion over time and eventually leads to insulin resistance and T2DM." (PMID 24367371, 2013). "Fasting glucose and insulin levels were collected at each time point; and insulin resistance was estimated by the homeostasis model assessment (HOMA-IR)." (PMID 24084051, 2013). "Visceral adipose tissue is related to insulin resistance and insulin plays a role in the proliferation of osteoblasts." (PMID 23510224, 2013). "Small size at birth in humans consistently induces insulin resistance in adults and adolescents, but this is preceded by enhanced insulin sensitivity in neonates, which reverses to resistance in association with catch-up growth in the first few years of life." (PMID 23424667, 2013). "Peripheral insulin resistance has been reported to adversely affect insulin secretion, ultimately resulting in pancreatic exhaustion." (PMID 23776622, 2013). "In humans, when individuals initially experience insulin resistance, a compensatory process of β-cells is triggered to releasing more insulin into the bloodstream to match the increased demand of insulin for glucose disposal." (PMID 24167617, 2013). "ROS are involved both in insulin signal transduction and in insulin resistance when produced in excess." (PMID 23618488, 2013). "Adiponectin exerts a potent insulin-sensitizing effect, activates the glucose uptake, protects against insulin resistance, and acts as anti-inflammatory protein." (PMID 23690866, 2013).
Insulin resistance (continued). "is the uncompensated phase of insulin resistance when the secretory capacity of insular β-cells becomes exhausted and the decreased serum insulin level results in hyperglycemia." (PMID 23061769, 2013). "Muscle FGF-21 mRNA correlated positively to all markers of insulin resistance: fasting insulin (r = 0.57, p = 0.0008), homeostasis model assessment (HOMA) score (r = 0.55, p = 0.001), and insulinAUC (r = 0.38, p = 0.02)." (PMID 23533568, 2013). "Insulin resistance (IR) is a pathological state in which the effects of insulin on peripheral tissues are reduced, primarily as a result of overeating, obesity and lack of physical activity." (PMID 24358272, 2013). "An adaptive response of the decline in IRS-1m impaired the ability of insulin to promote glucose utilization, hence leading to the development of insulin resistance." (PMID 24312573, 2013). "There was a trend toward an improvement in insulin sensitivity, as measured by homeostasis model assessment of insulin resistance (HOMA-IR) in both the WT and the GKO mice treated with MK-0916." (PMID 24169553, 2013). "Our results indicated that serum glucose level, fasting insulin level and homeostasis model assessment of insulin resistance (HOMA-IR) in OS were significantly lower compared to those of the HS (p < 0.01, p < 0.05, p < 0.05)." (PMID 23538842, 2013). "In insulin resistance, the ability of insulin to stimulate glucose disposal is impaired and compensated for by an increase in insulin secretion from the beta cells of the pancreas." (PMID 22828963, 2013). "Insulin resistance, characterized by reduced responsiveness to normal circulating concentrations of insulin, is a common feature of almost all patients with T2DM, and it plays a key role at the beginning and in the development of whole process of T2DM." (PMID 23671868, 2013). "Insulin resistance is clinically defined as the inability of a known quantity of insulin (exogenous or endogenous) to increase glucose uptake and utilization in an individual as much as it does in a normal population." (PMID 23573411, 2013). "Similar to dysmetabolic humans, the DYS monkeys in the present study also showed marked hyperinsulinemia, a characterization of increased insulin resistance as defined by HOMA-IR or decreased insulin insensitivity as defined by QUICKI." (PMID 23886319, 2013). "In recent years, investigators emphasize the role of cytokines and especially adipocytokines that influence insulin sensitivity as biomarkers of early impaired glucose metabolism and insulin resistance." (PMID 24260557, 2013). "In the setting of insulin resistance, insulin is unable to properly suppress lipolysis, resulting in an increase in free fatty acid release into the plasma." (PMID 23533500, 2013). "Overexpression of PTP1B has been linked to insulin resistance in peripheral tissues of ob/ob mice and PTP1B knockout mice display increased insulin sensitivity." (PMID 24252636, 2013). "In the present study, fasting insulin levels and estimated insulin resistance was calculated by HOMA index." (PMID 24639763, 2013). "MCP-1 is an adipokine with insulin-resistance-inducing capacity that is related to increased adipose tissue mass in obesity and insulin resistance." (PMID 23533500, 2013). "We determined levels of insulin and adiponectin as markers of insulin resistance, and of IGF-1 as a hormone sensitive to the diet." (PMID 23451233, 2013). "Insulin resistance is thought to be mediated by the release of pro-inflammatory molecules and other mediators from adipocytes and inflammatory cells which alter insulin response in fat and muscle tissue." (PMID 23527073, 2013). "Several other adipose-derived hormones oppose insulin action, and they circulate at increased levels in obesity, thus also possibly contributing to insulin resistance." (PMID 23497617, 2013). "Adiponectin acts to improve insulin sensitivity and serum concentrations are reduced in obese, insulin resistance humans." (PMID 24348462, 2013).